GATA1 (GATA binding protein 1)
Diseases named in the same sentence as GATA1 in open-access papers (continued):
Sharing a sentence is not in itself a finding about the gene and the disease.
leukemia (45 papers, 2006 to 2025). A malignant (clonal) hematologic disorder, involving hematopoietic stem cells and characterized by the presence of primitive or atypical myeloid or lymphoid cells in the bone marrow and the blood. "In leukemia, GATA1 mutations are involved in the pathogenesis of acute megakaryoblastic leukemia (AMKL) and transient myeloproliferative disorder (TMD) in Down syndrome patients." (PMID 41514651, 2025). "Our analysis results hinted that the dysregulation of GATA1 during leukemia progression was likely associated with its upstream SE." (PMID 37194711, 2023). "Recently, it was shown that preleukemia to leukemia transition in fetal liver trisomic HSCs was mediated by mutations in cohesion genes in addition to GATA1." (PMID 35203280, 2022). "CTCF mutations, when layered onto GATA1 mutation, potentiate evolution into clinical leukemia, defined by unlimited replicative potential and impaired ability to differentiate." (PMID 36037342, 2022). "Over the course of 6 months Dox treatment, several mice harboring Gata1- or Xbp1-deficient leukemia succumbed to relapse, however overall survival was significantly improved relative to controls (p = 0.016 or 0.002, Mantel-Cox test)." (PMID 34764270, 2021). "Consistent with earlier transplants, control and Gata1 knockout cells engrafted recipient mice with comparable kinetics and caused overt leukemia within a few weeks." (PMID 34764270, 2021). "The immediate in vivo Dox response of Gata1-deficient and control leukemias was similar, with acute GFP repression and regression within 2 weeks." (PMID 34764270, 2021). "Recently, it was reported that trisomy 21 upregulates insulin-like growth factor (IGF) signaling to enhance the GATA1 expression aberrantly, thereby causing leukemia in DS." (PMID 31963583, 2020). "The diagnosis of mosaic DS and TAM was confirmed with abnormal GATA1 mutation testing, highlighting the importance of early GATA1 mutation testing in newborn leukemia with high suspicion for TAM." (PMID 32481622, 2020). "Increased sensitivity to Ara-C was reported to be due to increased expression of the enzyme cystathionine-[β]-synthase (CBS), and to the presence of somatic mutations in the transcription factor gene GATA-1 in leukemia cells of patients with DS-AMKL." (PMID 28143565, 2017). "Perhaps fewer additional, acquired aberrations are needed to establish the leukemia because of the presence of the “preleukaemic” trisomy 21, akin to what has been suggested for ML-DS, in which GATA1 mutations are only efficient in the context of +21c." (PMID 24726034, 2014). "In fact, although GATA-1 mutations are a common hallmark of ML-DS cases and are critical for leukaemia progression, the development of ML-DS requires a third hit represented by the acquisition of additional molecular defects, predominantly in cohesin complex genes such as STAG2." (PMID 38350611, 2024). "However, they do not develop overt megakaryoblastic leukaemia, likely because progression to leukaemia requires mutations in Gata1 and other genes." (PMID 34477842, 2021). "Such up-front Dox resistance of immature leukemia cells may occur in both parental AML246 and its Gata1-deficient or Xbp1-deficient derivatives, and may contribute to the low frequency relapses observed with eosinophil-incapable leukemias." (PMID 34764270, 2021). "Therefore, attempts have been made to understand the synergy between the unique combination of trisomy 21 and GATA1 mutations in inducing leukemia." (PMID 33102613, 2020). "However, it has been reported that three copies of the RUNX1, ETS2, and ERG genes on chromosome 21 interplay with somatic GATA1 mutations on the X chromosome to increase the risk of leukemia in DS." (PMID 31963583, 2020). "In these settings, Gata1.05-driven leukemia manifested in autosomal dominant patterns within the 129X1/SvJ background and in autosomal recessive patterns within C57BL/6J background." (PMID 38409047, 2024).
leukemia (continued). "Only 6 of 18 mice harboring Gata1 knockout leukemia and 1 of 12 mice with Xbp1 knockout leukemia relapsed within a 6-month period on Dox, compared with 14 of 21 control mice." (PMID 34764270, 2021). "Transcription factor binding motif analyses in gene promoters divulged two transcription factors possibly regulating the expression of these genes, i.e., RXRA and GATA1, which are important for leukemia and erythroid development, respectively." (PMID 34832908, 2021). "Children with DS have an increased risk of developing leukaemia, and among neonates and infants, AML is associated with GATA-1 recurrent mutations." (PMID 29225689, 2017). "Since Gata1 is one of the most highly up-regulated genes in erythroblasts of E/F; Mx1-cre animals, Gata1 immunostaining was used as a reliable biomarker in the leukemia mouse model to trace erythroblasts." (PMID 26462019, 2015). "As GATA1 is a master regulator of erythropoiesis and K562 is a leukaemia derived cell line, the HudsonAlpha HDAC2 experiment (and antibody) appears more reliable than the Broad HDAC2 in K562." (PMID 26619763, 2015). "EWS-FLI1 induced leukemia resulted in overpopulation of bone marrow with Gata1 positive cells, which was significantly reduced in YK-4-279 treated animals." (PMID 26462019, 2015). "Sixteen of the corresponding transcription factors are of particular interest, as they are housekeeping genes or show a direct link to hematopoiesis, tumorigenesis or leukemia (e.g. GATA-1/2, PU.1, MZF-1)." (PMID 19587786, 2009). "However, when GATA1s is expressed at levels significantly exceeding that of endogenous GATA1, the development of leukemia was restrained in a dose dependent manner." (PMID 38409186, 2024). "Based on these observations, it has been proposed that dysregulated miRNA-mediated gene expression might cooperate with GATA-1S in promoting pre-leukaemia in DS or contribute to control GATA-1 expression levels." (PMID 38350611, 2024). "The regulatory mechanism of GATA1 and SE in leukaemia was still unclear." (PMID 37194711, 2023). "In summary, we identified specific signaling pathways by which co-operative mutations in GATA1 and STAG2 may develop leukemia in a trisomy background." (PMID 35203280, 2022). "Reduced Gata1 expression could lead to the emergence of leukemia and bone marrow fibrosis with the accumulation of immature MKs." (PMID 34502524, 2021). "For instance, GATA1 mutations could affect both megakaryopoiesis and erythropoiesis, whereas variants of RUNX1 and ETV6 are involved in leukemia predisposition." (PMID 34502524, 2021). "GATA-1 mutation is present in transient abnormal myelopoiesis (TAM), a clonal pre-leukaemia condition that occurs in about 10% of neonates with DS, presenting at a median age of 3–7 days with the accumulation of megakaryoblasts, increased leukocytes and thrombocytopenia." (PMID 29225689, 2017). "Despite perturbations of hematopoietic development in the Ts1Cje, Ts65Dn and Tc1 models of DS, these mice do not develop leukaemia, even when the trisomic models also express disease-associated GATA1 mutations." (PMID 23554618, 2010). "It is possible that trisomy of Hsa21 genes other than those encoded in these models, in concert with mutations in non-Hsa21 encoded genes such as GATA1, JAK3 or CRLF2, may be required for the development of leukemia." (PMID 23554618, 2010). "Gata1 is equally highly expressed in the erythroid and in the megakaryoblastic leukaemias." (PMID 20102610, 2010). "Additionally, we compiled and analyzed ChIP-seq data from erythroid cell lines, K562 (human leukemia cell line) and G1E/G1E-ER (mouse erythroid cell lines that are derived from Gata1-null erythroid cells containing an estrogen-inducible Gata1 transgene; herein G1E)." (PMID 25521328, 2014).
leukemia (continued). "Targeting GATA1 and GATA2 in leukemia can potentially disrupt leukemic stem cell self-renewal and promote differentiation, offering novel avenues for AML and MDS treatment." (PMID 41514651, 2025). "These splicing perturbations alter the composition of numerous hematopoietic stem and progenitor (KLF2, GATA2, GATA1, SPINK2) or leukemia (LAT2 and NUCB2) regulatory factors." (PMID 36697445, 2023). "A comparison of selected gene activities in 93 leukemia cell lines using data from the Human Protein Atlas showed elevated expression of TBX1 and GATA1 and low levels of GNAI2 in K-562, confirming our findings." (PMID 38203204, 2023). "Although more studies are required to better clarify the regulatory network involving GATA-1 and HIF-1α in normal and aberrant hematopoiesis, these finding shed new light on the molecular mechanisms leading to metabolic rewiring in leukemia cells." (PMID 34679737, 2021). "We examined the RNA expression of three hematopoietic GATA transcription factors (GATA1, GATA2, and GATA3) in a total of 1,644 pediatric leukemia patients with AML (n = 297), T-ALL (n = 99), and B-ALL (n = 1,248) using RNA-seq data available at St." (PMID 35087776, 2021). "For example, for GATA1, we found several cell-type specific co-regulators such as HNF1 in hematopoietic progenitor cells, PPARA:RXRA in leukemia and a general co-regulator EVI1 found to cooperate with GATA1 in more than 15 cell types." (PMID 30142147, 2018). "Our data together suggest that RNA and hnRNPK mediate 5-AZA-sensitive interactions between the lineage-determining factors (GATA1 and SPI1/PU.1) and chromatin modifiers in the OCI-M2 and SC leukaemia cells." (PMID 29563491, 2018). "In an initial examination of Gata1.05/X mice backcrossed into C3H/He, BALB/c, DBA/2, C57BL/6J and 129X1/SvJ strains, we discerned that the backgrounds of C57BL/6J and 129X1/SvJ significantly expedited leukemia onset in Gata1.05/X mice." (PMID 38409047, 2024). "Although it is currently unknown if GATA-1S has a direct role in the alteration of the splicing machinery, our results clearly indicate that, along with unbalanced GATA-1 isoform ratio, aberrant expression of SDHC ASVs emerges as a leukemia-promoting factor." (PMID 34679737, 2021). "Hence, Gata1 and Xbp1 are dispensable in immature AML246 leukemia cells but essential for leukemia maturation into the eosinophil lineage following in vivo differentiation therapy." (PMID 34764270, 2021). "In contrast, Dox-induced differentiation of Gata1 knockout leukemia failed to produce mCherry+SSCHIGHSiglecF+ eosinophil-like cells." (PMID 34764270, 2021). "For example, GATA1 partners with HNF1 in hematopoietic progenitor cells; with PPARA:RXRA in leukemia; with SRF, CDX and FOXP3 in primary T-cells; with SRY, NKX2-1, FOXF1, OCT4 and ZBTB16 in differentiated ESCs and with TAL1:TCF3 motif co-occurring in various fibroblasts." (PMID 30142147, 2018). "TF_3 contained TFBSs for GATA1/2 and TAL1, essential in hematopoietic and leukemia cells." (PMID 28700586, 2017). "These surprising results suggest that DYRK1A and GATA1 may synergistically restrain megakaryocyte proliferation in T21 and that DYRK1A inhibition may not be a therapeutic option for GATA1s-associated leukemias." (PMID 37906251, 2023). "Notably, Thy1.1+ cell representation was maintained following leukemia transplant and engraftment in recipient mice, indicating that Gata1 knockdown does not affect immature leukemia cells as predicted." (PMID 34764270, 2021). "Hence, consistent with its role in normal GMPs, Gata1 suppression in vivo has no discernible effect on the proliferation of immature (GMP-like) AML246 or its neutrophil derivatives but blocks leukemia-derived eosinophil maturation." (PMID 34764270, 2021). "However, key lineage specific transcription factors (PU.1, GATA-1, IKAROS, PAX5) were not differentially expressed in HSPCs, suggesting that the immunocompetent leukemia microenvironment may contribute to deregulation of hematopoiesis." (PMID 33154494, 2020).
Down syndrome (43 papers, 2009 to 2026). "For example, individuals with Down syndrome have increased risk of haematological malignancies due to GATA1 mutations on the short arm of X chromosome." (PMID 41497315, 2026). "GATA1 mutations are normal in transient myeloproliferative disorder and acute megakaryoblastic leukemia in children with Down syndrome (DS), leading to leukemogenesis." (PMID 39887881, 2025). "We also note a case of Down syndrome–associated AML-EMD that highlights an alternative GATA1-driven pathogenesis of dual erythroid and megakaryocytic differentiation." (PMID 41408008, 2025). "In contrast to other types of congenital acute leukemia and myeloproliferative tumors, TAM and ML-DS occur in children with trisomy 21 syndrome and are often accompanied by mutations in the key hematopoietic transcription factor GATA1 gene." (PMID 40696625, 2025). "Acquired mutations in the hematopoietic transcription factor GATA1 are found in megakaryoblasts of nearly all individuals together with Down syndrome with TAM and the related acute megakaryoblastic leukemia (DS-AMKL, also called DS-AML M7)." (PMID 37858167, 2023). "The mutation of GATA1 gene is essential in the development of Down syndrome combined with TAM or ML-DS." (PMID 37858167, 2023). "Mutations in the GATA1 gene are thought to be a pathognomonic feature of all myeloproliferative disorders in children with Down syndrome, including those with TAM." (PMID 37858167, 2023). "For instance, Down syndrome, one of the leading causes of ID, is related to the presence of somatic mutations in GATA1 and JAK2, which are associated with acute megakaryoblastic leukemia and ALL." (PMID 34673770, 2021). "Excluding Down syndrome newborns harboring preleukemic GATA1 mutations (N = 30), identified by targeted sequencing, has minimal impact on the epigenome-wide association study results." (PMID 33547282, 2021). "Acute myeloid leukemia in Down syndrome children is characterized by the mutation in GATA1, resulting in N-terminally truncated mutant GATA1 (GATA1s)." (PMID 33102613, 2020). "Mutation of GATA1 leads to acute megakaryoblastic leukemia (AMKL) in infants with Down syndrome and transient myeloproliferative disorder (TMD)." (PMID 31093285, 2019). "Somatic mutations in GATA1, preventing the synthesis of GATA1-FL, predispose newborn Down Syndrome (DS) patients to develop (in 10–20% of cases) transient myeloproliferative disease (TMD)." (PMID 30809156, 2019). "Nearly all cases of transient leukemia and Down syndrome associated AMKL have N-terminal truncating GATA1 mutations (GATA1-Short) present at birth that become undetectable after transient leukemia and AMKL remission." (PMID 31628330, 2019). "A further 10–15 % of neonates with Down syndrome have one or more acquired GATA1 mutations in association with a low number of circulating blast cells (<10 %) and have clinically and haematologically silent disease (silent TAM) [11••]." (PMID 27510823, 2016). "GATA1 mutations are found in nearly allAMKL patients with Down syndrome and are already detectable in the precursor lesion TMD.In addition, Down syndrome-neonates without GATA1 mutations do notdevelop AMKL (Refs 159, 160)." (PMID 26953528, 2016). "At least half of all Down syndrome neonates with GATA1 mutations have a peripheral blood blast percentage of 1–10 % and have no clinical features associated with TAM [11••]." (PMID 27510823, 2016). "Acquired somatic mutations of GATA1 have been consistently detected in nearly all Down syndrome TAM and AMKL cases." (PMID 26445707, 2015). "Down syndrome patients with somatic mutations in GATA1 have favorable prognosis, with 90% remission rates and 60%-70% event-free survival." (PMID 25805677, 2015). "Acute megakaryocytic leukemia (AMkL) in Down syndrome (DS) children is uniformly associated with somatic GATA1 mutations, which result in the synthesis of a shorter protein (GATA1s) with altered transactivation activity compared to the wild-type GATA1." (PMID 22110660, 2011).
Down syndrome (continued). "In contrast, patients with the Down syndrome (trisomy 21) are prone to cellular selection of acquired somatic GATA-1 mutations that produce GATA-1s and result in preleukemic myeloproliferative disorders." (PMID 19513100, 2009). "Pathogenic GATA1 variants were identified in all five patients with Down syndrome." (PMID 39975890, 2025). "Acquired GATA1 mutations resulting in expression of GATA1s are common in Down Syndrome patients with trisomy 21, causing transient abnormal myelopoiesis that may spontaneously resolve or progress to AML." (PMID 37377909, 2023). "AMKL associated with Down syndrome (DS) shows GATA1 mutations and has a favorable prognosis." (PMID 37325571, 2023). "The myeloid proliferations related to Down syndrome—transient abnormal myelopoiesis and myeloid leukemia—have unique morphologic, immunophenotypic, clinical, and molecular features, including GATA1 mutation, that justify their separation from other myeloid neoplasms." (PMID 37858167, 2023). "The diagnosis of TAM requires a GATA1 mutation as well as an increase in blasts and/or certain clinical features (especially hepatosplenomegaly) in neonate with Down syndrome and may also be mosaic." (PMID 37858167, 2023). "GATA1 mutation is known to play an important role in Down Syndrome (DS) associated AMKL." (PMID 33668444, 2021). "GATA1 structural mutations were found in Down syndrome patients with megakaryocytic leukemia." (PMID 34832908, 2021). "GATA1 s is frequently expressed in acute megakaryoblastic leukemia in patients with Down syndrome due to mutations in exon 2 that affect splicing and might be relevant for the development of this disease." (PMID 29884215, 2018). "Nearly all Down syndrome patients with AMKL harboursomatic mutations in the GATA1 gene (Ref." (PMID 26953528, 2016). "Together, the presence of GATA1 mutationsin Down syndrome-children might be a potential prognostic marker for identifying infantsat higher risk of developing AMKL (Ref." (PMID 26953528, 2016). "Besides these deficiencies, patients with Down syndrome are more likely to develop an acquired, i. e. somatic, GATA1 mutation leading to a truncated form of GATA1 (GATA1s)." (PMID 27152938, 2016). "AMKL predominates in children with Down syndrome and is associated with somatic GATA1 mutations." (PMID 25805677, 2015). "As well as being of general interest to understanding of haematopoiesis, GATA1 isoform biology is important for children with Down syndrome associated acute megakaryoblastic leukaemia (DS-AMKL) where GATA1FL mutations are an essential driver for disease pathogenesis." (PMID 22853316, 2012). "Recent studies have suggested that environmental factors may play a role in the development of GATA1 mutations, as epigenome-wide association studies have linked a metastable epiallele (VTRNA2-1) to a differentially methylated GATA1 region associated with Down Syndrome." (PMID 37377909, 2023). "Individuals with Down syndrome (DS) frequently have hematopoietic abnormalities, including transient myeloproliferative disorder and acute megakaryoblastic leukemia which are often accompanied by acquired GATA1 mutations that produce a truncated protein, GATA1s." (PMID 29435140, 2018). "However, GATA1 mutation appears to be the initiating events in the Down syndrome leukemogenesis." (PMID 26445707, 2015). "For example, two patients with Down Syndrome (SJ030077, 13% blasts; SJ031477, 5% blasts) showed GATA1 variants at 4.8% and 3.1%, respectively." (PMID 39975890, 2025). "In a pediatric cohort of Non-Down Syndrome AMKL, mutation of GATA1 was the most common recurrent mutation, with patients harboring truncating mutations in either exon 2 or 3 (11–13,5%)." (PMID 33668444, 2021). "GATA1 isoform biology is particularly important for children with Down syndrome and a subset of children born with Diamond-Blackfan anemia." (PMID 31628330, 2019).